TRINGS (TP53 regulated inhibitor of necrosis under glucose starvation)
Synonyms: LOC105377329
Gene: Long non-coding RNA gene on chromosome 4 (89,410,875 to 89,741,804, forward strand). Ensembl gene ENSG00000251095.
Diseases named in the same sentence as TRINGS in open-access papers:
TRINGS is named in the same sentence as 2 diseases in open-access papers, as found by Europe PMC text mining. Sharing a sentence is not in itself a finding about the gene and the disease. The quoted sentences say what the papers report.
cancer (5 papers, 2019 to 2023). A tumor composed of atypical neoplastic, often pleomorphic cells that invade other tissues. "It has been suggested that lncRNA TRINGS protected cancer cells from death by inhibiting STRAP-GSK3β-NF-κB necrotic signaling." (PMID 37504305, 2023). "TRINGS physically interacts with STRAP and inhibits STRAP-GSK3B-NF-κB necrotic signaling to protect cancer cells against necrosis." (PMID 35842651, 2022).
tumor (1 paper, 2021). "TRINGS binds STRAP (serine–threonine kinase receptor-associated protein) and inhibits STRAP-GSK3β-NF-κB necrotic signaling to protect tumor cells from cell death." (PMID 33558499, 2021).